ASCL2 (achaete-scute family bHLH transcription factor 2)
Description:
Transcription factor. Binds to E-box motifs 5'-CANNTG-3' in the regulatory elements of target genes, probably as a heterodimer with another basic helix-loop-helix (bHLH) protein such as the transcription factor TCF3. May bind both open and closed chromatin, acting as a pioneer transcription factor to allow other factors to bind and activate lineage-specific genes. Required during post-implantation development for the generation of some differentiated trophoblast cell types. Transcriptional activity of ASCL2 may be antagonised in a subset of trophoblast cells by bHLH transcription factor HAND1, perhaps by competing for dimerization with other bHLH proteins. Involved in differentiation and function of follicular T-helper (Tfh) cells, thereby playing a role in germinal center responses; probably modulates expression of genes involved in Tfh cell function, such as BCL6. May also act as a suppressor of Th1-, Th2- and Th17-cell differentiation. Induces the formation of stem cells in intestinal crypts in vitro, synergistically activating transcription of target genes, such as SOX9, together with TCF4/beta-catenin. May form a bistable transcriptional switch, controlling expression of its own gene together with Wnt/R-spondin signaling, and thereby maintaining stem cell characteristics (By similarity). Modulates expression of target genes, including perhaps down-regulating EGR1/Krox24 and chemokine CXCL10/Mob-1 and up-regulating CXCR4 and CDKN1C/p57kip2, in Schwann cells. May play a role in reducing proliferation of Schwann cells, perhaps acting via modulation of expression of CDKN1C (By similarity). May be dispensable for blastocyst formation and later embryonic function (By similarity). May be involved in the determination of neuronal precursors (By similarity).
Synonyms: hASH2; bHLHa45; ASH2; MASH2
Tractability: No criterion of Open Targets' tractability assessment is met for any kind of drug.
Gene: Protein-coding gene on chromosome 11 (2,268,498 to 2,270,588, reverse strand). Ensembl gene ENSG00000183734.
Subcellular location: Nucleus
Gene Ontology:
Molecular function: DNA-binding transcription repressor activity, RNA polymerase II-specific; E-box binding; RNA polymerase II cis-regulatory region sequence-specific DNA binding; sequence-specific double-stranded DNA binding; DNA-binding transcription factor activity, RNA polymerase II-specific; RNA polymerase II transcription regulatory region sequence-specific DNA binding; bHLH transcription factor binding; DNA-binding transcription activator activity, RNA polymerase II-specific; DNA-binding transcription factor activity; protein dimerization activity; sequence-specific DNA binding
Biological process: negative regulation of transcription by RNA polymerase II; response to hypoxia; spongiotrophoblast layer development; neuron differentiation; placenta development; positive regulation of transcription by RNA polymerase II; regulation of neurogenesis; sensory organ development; chorionic trophoblast cell development; negative regulation of Schwann cell proliferation; negative regulation of T-helper 1 cell differentiation; negative regulation of T-helper 17 cell differentiation; negative regulation of T-helper 2 cell differentiation; positive regulation of T cell migration; regulation of transcription by RNA polymerase II; stem cell population maintenance; T follicular helper cell differentiation
Cellular component: cytoplasm; nucleus; chromatin; RNA polymerase II transcription regulator complex
Genetic constraint (gnomAD): Loss-of-function variants: 6 observed, 2.79 expected, observed/expected ratio (o/e) 2.15. That is too few expected variants to judge how well the gene tolerates losing a copy. Missense variants: 320 observed, 176.35 expected, observed/expected ratio (o/e) 1.81, 90% interval 1.65 to 1.96. Synonymous variants: 174 observed, 100.15 expected, observed/expected ratio (o/e) 1.74, 90% interval 1.53 to 1.93.
Homologues: Orthologues: chimpanzee ASCL2 (99% identical), macaque ASCL2 (96% identical), dog ASCL2 (87% identical), pig ASCL2 (85% identical), guinea pig ASCL2 (80% identical), mouse Ascl2 (74% identical), rat Ascl2 (70% identical), zebrafish ascl1a (47% identical), zebrafish ascl1b (47% identical), Drosophila melanogaster l(1)sc (31% identical), Drosophila melanogaster ase (28% identical), Drosophila melanogaster sc (27% identical), and 2 more. Paralogues in human: ASCL1 (49% identical), ASCL5 (26% identical), ASCL4 (25% identical), ASCL3 (22% identical).
Diseases named in the same sentence as ASCL2 in open-access papers:
ASCL2 is named in the same sentence as 59 diseases in open-access papers, as found by Europe PMC text mining. Sharing a sentence is not in itself a finding about the gene and the disease. The quoted sentences say what the papers report.
colorectal cancer (34 papers, 2013 to 2026). A primary or metastatic malignant neoplasm that affects the colon or rectum. "ASCL2, a key player in tumor progression and metastasis, has been studied in other cancers, including colorectal cancer, consistently associated with poor prognosis." (PMID 35154991, 2022). "The results demonstrate that Ascl2 is a promising target for immunoprevention for individuals at elevated risk of developing colorectal cancer." (PMID 33671373, 2021). "Furthermore, recent studies have revealed that ASCL2 is associated with immune infiltration in colorectal cancer." (PMID 35774798, 2022). "In addition, ASCL2 was linked to drug resistance in colorectal cancer cells." (PMID 38252116, 2024). "Achaete scute‐like 2 (ASCL2), a downstream target of the Wnt/β‐catenin signaling pathway, is a helix–loop–helix transcription factor that is overexpressed in colorectal cancer and is considered an oncogene that promotes proliferation and liver metastasis." (PMID 35670012, 2023). "Subsequently, we identified Ascl2 as the main gene affecting the stemness of colorectal cancer in AT7867 by RNA sequencing." (PMID 36824410, 2023). "Decreased Ascl2 gene expression leads to reduced tumorigenicity of colorectal cancer cells and the expression of stemness-related markers." (PMID 36824410, 2023). "Microsatellite stable colorectal cancer samples overexpressing ASCL2 were shown to have low CD8+ T cell infiltration." (PMID 35774798, 2022). "As a basic helix-loop-helix transcription factor, ASCL2 promotes the self-renewal ability of colorectal cancer progenitor cells." (PMID 35470736, 2022). "The H3K27ac level of ASCL2 enhancer greatly increased in tumors, and the gene expression analysis based on TCGA datasets suggested ASCL2 was highly expressed specific in colorectal cancer." (PMID 34737287, 2021). "The goal of the present study was to determine the efficacy of a protein-based vaccine targeting Ascl2 in combination with an anti-PD-1 treatment in a spontaneous colorectal cancer mouse model." (PMID 33671373, 2021). "First, Ascl2 participates in Wnt signaling, a pathway activated in the majority (>80%) of sporadic and familial colorectal cancers." (PMID 33671373, 2021). "Otherwise, when working with colorectal cancer organoids, make sure ASCL2 is still expressed in this tissue." (PMID 33377020, 2020). "Another stem cell marker achaete-scute complex homolog 2 (Ascl2) is suggested to regulate the development of colorectal cancer via CDX2." (PMID 28160571, 2017). "ASCL2 overexpression is observed in colorectal cancers, and ASCL2 overexpression shifts the hierarchy of stem/progenitor cells in liver metastases and affects clinical outcomes." (PMID 28757546, 2017). "Positive correlation among YAP1 and Ascl2 mRNA levels was observed in colorectal cancer (CRC) samples." (PMID 29312609, 2017). "Ascl2 is over-expressed in colorectal cancer, shifting the hierarchy of stem and progenitor cells in liver metastases and results in self-renewal rather than differentiation." (PMID 26307678, 2015). "Liver metastases from colorectal cancer exhibit an ASCL2-related stem cell signature which likely influences the metastatic activity of tumor cells." (PMID 23969837, 2013). "A recent study also links ASCL2 expression to early-onset colorectal cancer in a Japanese cohort." (PMID 39895630, 2025). "Further, HMGA1 and ASCL2 are coexpressed and upregulated in human colorectal cancer." (PMID 39895630, 2025). "HMGA1 and ASCL2 are upregulated and coexpressed in human colorectal cancer." (PMID 39895630, 2025). "Moreover, a vaccine targeting ASCL2 was shown to affect the efficacy of anti-PD-1 in colorectal cancer." (PMID 35774798, 2022). "The achaete-scute family bHLH transcription factor 2 (Ascl2) has been identified as a promising target for immunoprevention of colorectal cancer, based on its induction during the formation and progression of colorectal tumors and its minimal expression observed in healthy tissue." (PMID 33671373, 2021).
colorectal cancer (continued). "In addition, recurrent focal genomic amplification spanning IGF2, WiNTRLINC1, and ASCL2 genes was detected in 9.9% of colorectal carcinomas and 2.7% of stomach adenocarcinomas." (PMID 34538872, 2021). "In colorectal carcinomas, Snail1 could combine with the competitive displacement of ASCL2 and epigenetic mechanisms to rapidly silence the EPHB3 tumor suppressor." (PMID 31271097, 2019). "Ascl2 is abundantly expressed in colorectal cancer; has the potential to shift the hierarchy of stem and progenitor cells during liver metastasis, resulting in self-renewal rather than differentiation; and potentially affects the clinical behavior of these tumors." (PMID 29312609, 2017). "The role of Achaete scute-like 2 (Ascl2) in colorectal cancer (CRC) cell differentiation is unknown." (PMID 26307678, 2015). "They found the G protein-coupled receptor (lgr5) and intestinal stem cells signature gene (Ascl2) was expressed on mainly colorectal cancers, which supported the hypothesis that the cancer cells were derived from lgr5+/Ascl2+ crypt stem cells." (PMID 26056577, 2014). "Furthermore, Wnt signaling pathway plays an important role in the maintenance of CSCs, but elevated expression of several Wnt target genes, including ASCL2 and LGR5, is actually associated with good prognosis in colorectal cancer." (PMID 25237769, 2014). "Hence, dysregulated ASCL2 expression is thought to facilitate colorectal cancer cell proliferation." (PMID 28757546, 2017). "LINC01315 was also found to be correlated with DPEP1, KRT23, ASCL2, AXIN2, and DUSP4 in colorectal cancer." (PMID 35470736, 2022). "Recent studies have reported that ASCL2 may contribute to the pathogenesis of autoimmunity and immune resistance in Sjögren syndrome, colorectal cancer, and lung adenocarcinoma; however, the mechanism underlying the role of the ASCL2 in inflammation in stomach carcinoma has not been explained." (PMID 36008864, 2022). "Ascl2 plays a critical role in intestinal stem cells, CRC progenitor cells and human colorectal cancer and is also overexpressed in gastric cancer and lung squamous cell carcinoma." (PMID 29312609, 2017). "To test our hypothesis that reduced CD8+ T cell infiltration by ASCL2 limits the response to anti-PD-L1 in CRCs, we studied the MC38 mouse colorectal cancer model." (PMID 37591954, 2023). "Importantly, ASCL2 plays an indispensable role in LGR5+ intestinal stem cells and colorectal cancer progenitor cells." (PMID 35670012, 2023). "ASCL2 and LGR5 are two important target genes of Wnt signaling in colorectal cancer." (PMID 35299743, 2022). "Recent evidence suggests that not all patient-derived colorectal cancer cell lines express ASCL2, which constitutes a natural but hitherto not encountered limit." (PMID 33377020, 2020). "In colorectal cancer cells, with the assistance of a neighboring cis-acting lincRNA, TCF4/β-catenin complex was recruited to the Ascl2 enhancer immediately downstream of the Ascl2 locus to drive high-level Ascl2 expression." (PMID 33109217, 2020). "Interestingly, the proteins ASCL2 and ITF-2B as well as ID1 and ITF-2B are known to interact with each other, suggesting that these bHLH proteins form a functional network in colorectal carcinoma cells." (PMID 24467841, 2014). "To further investigate whether the Lgr5+ cells in human GAs had any stem cell properties, we analyzed the levels of ISC markers such as ASCL2, EPHB2, and OLFM4, which are highly expressed in stem-like cells from human colorectal cancers, as well as in murine intestinal adenomas." (PMID 24340024, 2013).
colon cancer (28 papers, 2012 to 2025). "The Apc+/Min−FCCC mouse model is susceptible to spontaneous colon tumorigenesis and vaccine administration against achaete-scute family bHLH transcription factor 2 (Ascl2), an early colon cancer antigen elicited strong humoral and cellular immune responses." (PMID 40437549, 2025). "HMGA1 directly induces ASCL2 by binding to its promoter and recruiting activating histone marks in human colon cancer cells." (PMID 39895630, 2025). "Restoration of ASCL2 only partially rescues proliferation in colon cancer cell lines with HMGA1 silencing, indicating that HMGA1 regulates additional networks during colon tumorigenesis." (PMID 39895630, 2025). "Further, silencing HMGA1 disrupts oncogenic properties (proliferation and clonogenicity), while reexpression of ASCL2 partially rescues oncogenic phenotypes in HMGA1-depleted human colon cancer cells." (PMID 39895630, 2025). "Luo and colleagues demonstrated that HMGA1 is directly bound to the ASCL2 promoter and activated ASCL2 expression in human colon cancer cells." (PMID 39895631, 2025). "Previous studies have shown that ASCL2 is not only a transcription factor, but also a marker of colon cancer stem cells." (PMID 35670012, 2023). "Together with our early reports regarding Ascl2, one of the stem cell markers of colon cancer, we herein investigated other well-known stem cell markers such as CD44V and CD133 at mRNA level in primary colon cancer." (PMID 37098074, 2023). "Overall, these results reveal that DPEP1 intensifies the drug resistance of tumor cells in an ASCL2‐dependent manner by enhancing the stemness of colon cancer cells." (PMID 35670012, 2023). "The results demonstrated that both DPEP1 and ASCL2 were highly expressed in colon cancer tissues compared to normal tissues." (PMID 35670012, 2023). "We then transfected HCT116 cells with pCMV or pCMV‐DPEP1, respectively, and the results indicated that overexpression of DPEP1 resulted in a significant increase in the expression of ASCL2 colon cancer cells." (PMID 35670012, 2023). "Bioinformatics analysis and experiments showed that the expressions of DPEP1 and ASCL2 in colon cancer tissues were markedly positively correlated." (PMID 35670012, 2023). "Functionally, DPEP1 expression increased the resistance of colon cancer cells to the chemotherapy drugs oxaliplatin and irinotecan in the ASCL2‐dependent manner." (PMID 35670012, 2023). "Our experiments showed that the downregulation of Ascl2 caused striking tumor growth inhibition and increased the differentiation of cancer cells in MC38 colon tumor models in C57BL/6 mice." (PMID 37591954, 2023). "According to recently published literature, achaete-scute homolog 2 (Ascl2), as the target molecule of the Wnt signaling pathway, is an important marker of colon cancer stem/precursor cells." (PMID 37373349, 2023). "In summary, DPEP1 binds to ASCL2 in colon cancer cells and enhances protein ASCL2 stability by inhibiting its ubiquitin‐proteasomal degradation." (PMID 35670012, 2023). "Achaete-scute family bHLH transcription factor 2 (ASCL2) is a transcription factor that is over-expressed in colon cancer." (PMID 35774798, 2022). "The results showed the enrichment of ASCL2 in colon cancer tissue is higher, while enrichment of DUSP4 is lower." (PMID 35774798, 2022). "Meanwhile, by immunohistochemistry, colon cancer tissues were found to express stronger ASCL2 than normal colon tissues." (PMID 35774798, 2022). "High mRNA expression of ASCL2 was detected in human colon cancer cell lines and colon cancer tissues." (PMID 35774798, 2022). "This study examines the ability of a KISIMA vaccine against achaete-scute family bHLH transcription factor 2 (Ascl2), an early colon cancer antigen, to reduce colon tumor formation by stimulating an anti-tumor immune response." (PMID 33671373, 2021). "(H) Immunofluorescence of Ascl2 showing IL-17 antibody largely abrogated C. rodentium-infection-induced colon cancer stem cell proliferation." (PMID 30543324, 2018).